CHI3L1 (chitinase 3 like 1)
Diseases named in the same sentence as CHI3L1 in open-access papers (continued):
Sharing a sentence is not in itself a finding about the gene and the disease.
bladder cancer (5 papers, 2021 to 2025). "Our findings revealed the association of CHI3L1 expression with invasive or chemotherapy-resistant bladder cancer." (PMID 37958973, 2023). "Despite our observation of a higher expression of CHI3L1 in patients with invasive or chemotherapy-resistant bladder cancer and the association of CHI3L1 with increased neutrophil infiltration, the cellular sources of CHI3L1 secretion in the cancer microenvironment remain elusive." (PMID 37958973, 2023). "In addition to being highly expressed in bladder cancer, CHI3L1 expression is also associated with disease-specific survival and metastasis-free survival." (PMID 37958973, 2023). "Therefore, in this study, we examined the association between CHI3L1 expression and immune cell infiltration, particularly neutrophil infiltration, in patients with bladder cancer by using the ESTIMATE algorithm and TIMER algorithm." (PMID 37958973, 2023). "Subsequently, the expression level of CHI3L1 mRNA significantly increased when bladder cancer cells (T24, UMUC14, BFTC909) were co-cultured with HL60-N cells." (PMID 37958973, 2023). "In this study, we investigated the relationship between CHI3L1 expression and neutrophil infiltration in bladder cancer." (PMID 37958973, 2023). "We observed higher expression of CHI3L1 in bladder cancer patients with invasive or chemotherapy-resistance." (PMID 37958973, 2023). "Further studies should explore the cellular origin of CHI3L1 secretion in bladder cancer and elucidate how it leads to increased neutrophil infiltration." (PMID 37958973, 2023). "Not only is CHI3L1 highly expressed in bladder cancer patient tissues, but higher concentrations of CHI3L1 are also detected in patient serum." (PMID 37958973, 2023). "Therefore, various cell types within the tumor microenvironment can enhance CHI3L1 expression in patients with invasive or chemotherapy-resistant bladder cancer." (PMID 37958973, 2023). "In summary, CHI3L1 may serve as an assessment factor for evaluating neutrophil infiltration status in bladder cancer." (PMID 37958973, 2023). "Additionally, CHI3L1 can promote bladder cancer cell migration and invasion by regulating EMT gene expression." (PMID 37958973, 2023). "Therefore, this study investigated the relationship between CHI3L1 level and protumor neutrophil infiltration in bladder cancer." (PMID 37958973, 2023). "In addition, neutrophils had the ability to regulate CHI3L1 expression in bladder cancer." (PMID 37958973, 2023). "Consequently, CHI3L1 may serve as a novel evaluation factor for the degree of neutrophil infiltration in advanced bladder cancer in those scheduled for chemotherapy." (PMID 37958973, 2023). "A molecular marker of interest is chitinase 3-like-1 (CHI3L1), which is elevated in various cancers, including bladder cancer." (PMID 37958973, 2023). "We evaluated the expression of CHI3L1 along with clinical parameters and neutrophil infiltration by using the publicly available dataset (GSE128959) and a bladder cancer cohort undergoing chemotherapy." (PMID 37958973, 2023). "Therefore, future studies should determine whether CHI3L1, through its regulation of POSTN expression and function, affects the response of patients with bladder cancer to chemotherapeutic drugs." (PMID 37958973, 2023).
brain infarction (5 papers, 2010 to 2020). Tissue necrosis in any area of the brain, including the cerebral hemispheres, the cerebellum, and the brain stem. "For that purpose we analyzed CHI3L1 transcription in acute, subacute and chronic brain infarction in humans." (PMID 20540736, 2010). "Comparison of CHI3L1 expression in different stages of brain infarction showed that YKL40 was abundantly expressed in astrocytes during acute phases and diminished to low levels in chronic infarcts." (PMID 20540736, 2010). "The current study was carried out to identify the spectrum of CHI3L1 expression in a variety of neurodegenerative and neurological diseases, the cellular origin of CNS CHI3L1, and in the case of brain infarction a comparison between acute and chronic expression." (PMID 20540736, 2010). "The third aim of this study was to follow CHI3L1 expression in different stages of brain infarct." (PMID 20540736, 2010). "CHI3L1 ISH signal and immunohistochemistry was co-localized with GFAP staining in all the tested diseases (e.g. AD and brain infarction." (PMID 20540736, 2010).
hippocampal atrophy (5 papers, 2018 to 2025). "A recent study showed an association between CHI3L1 expression levels and hippocampal atrophy, an early event in AD progression." (PMID 38473707, 2024).
Hypercholesterolemia (5 papers, 2012 to 2022). An increased concentration of cholesterol in the blood. "Prevalence and risk (odds ratio (95% confidence interval)) of hypercholesterolemia and low HDL at baseline according to single nucleotide polymorphisms (SNPs) of CHI3L1 in MONICA-10." (PMID 23071724, 2012).
injury (5 papers, 2011 to 2024). Damage inflicted on the body as the direct or indirect result of an external force, with or without disruption of structural continuity. "Looking at only the population of trauma patients, the concentrations of several proteins, including YKL-40 (CHI3L1), IL-6, IL-8, IFNγ, and others, were positively correlated with patient age." (PMID 38903094, 2024). "In this study, we identified CHI3L1 as a novel mediator of the immunosuppressive effects of hUC-MSCs and the therapeutic effect of hUC-MSCs on Con A-induced liver injury in mice." (PMID 33664231, 2021). "CHI3L1 was abundantly secreted by hUC-MSCs and knocking down CHI3L1 in hUC-MSCs alleviated its therapeutic effect on Con A-induced liver injury in mouse models." (PMID 33664231, 2021). "Collectively, our data showed that CHI3L1 was a novel MSC-secreted immunosuppressive factor and provided new insights into therapeutic treatment of immune-mediated liver injury." (PMID 33664231, 2021).
juvenile idiopathic arthritis (5 papers, 2016 to 2024). Juvenile idiopathic arthritis (JIA) is the term used to describe a group of inflammatory articular disorders of unknown cause that begin before the age of 16 and last over 6 weeks. "Several other joint inflammatory diseases, such as psoriatic arthritis (PsA) and juvenile idiopathic arthritis (JIA), are also diagnosed on the basis of Chi3l1 levels." (PMID 39769202, 2024). "ELISA was also used to measure CHI3L1 in the serum and in the synovial fluid (SF) of juvenile idiopathic arthritis (JIA) patients." (PMID 27826220, 2016).
lymphoma (5 papers, 2013 to 2025). A malignant (clonal) proliferation of B- lymphocytes or T- lymphocytes which involves the lymph nodes, bone marrow and/or extranodal sites. "ROC curve analysis revealed that CHI3L1 has high sensitivity and specificity in the diagnosis of lymphomas, suggesting that it is a potential diagnostic biomarker." (PMID 40260255, 2025). "This study aimed to investigate the expression of CHI3L1 in aggressive lymphomas and assess its potential as a diagnostic and prognostic biomarker." (PMID 40260255, 2025). "This study demonstrates that elevated CHI3L1 expression is strongly associated with lymphoma onset, progression, severity, and poor prognosis, underscoring its potential as both a diagnostic and prognostic biomarker." (PMID 40260255, 2025). "Our results indicate that CHI3L1 is highly expressed in aggressive lymphomas and is closely associated with poor prognosis." (PMID 40260255, 2025). "In our study, through prognostic analysis of the GSE31312 dataset, we found that high expression of CHI3L1 was strongly associated with poor prognosis in patients with aggressive lymphomas." (PMID 40260255, 2025). "This study investigates the expression of CHI3L1 protein in the peripheral blood of patients with aggressive lymphoma and healthy controls using enzyme-linked immunosorbent assay (ELISA)." (PMID 40260255, 2025). "Analysis of the GSE31312 dataset revealed that high CHI3L1 expression was strongly associated with poor lymphoma prognosis, as shown by Kaplan–Meier survival analysis (P < 0.05)." (PMID 40260255, 2025). "Subsequently, a prognostic analysis of CHI3L1 was conducted using the lymphoma tissue sample gene expression dataset GSE31312." (PMID 40260255, 2025). "Bioinformatics analysis revealed that CHI3L1 expression was significantly elevated in lymphoma samples compared to normal controls (p < 0.05), with diagnostic AUC values of 0.92, 0.99, and 0.93, indicating high diagnostic accuracy." (PMID 40260255, 2025). "The innovation of this study lies in the first systematic evaluation and validation of the expression characteristics and prognostic value of CHI3L1 in aggressive lymphoma." (PMID 40260255, 2025). "We quantified serum CHI3L1 protein expression levels in 184 patients with invasive lymphoma and 40 healthy individuals using ELISA." (PMID 40260255, 2025). "Future studies should expand the sample size, incorporate multicenter data for validation, and focus on the specific mechanism of action of CHI3L1 in aggressive lymphomas, especially its interactions with key signaling pathways and cellular processes." (PMID 40260255, 2025). "Comparison of the general data of patients with aggressive lymphoma in the CHI3L1 high-expression group and low-expression group." (PMID 40260255, 2025). "In this study, we systematically investigated the expression characteristics of CHI3L1 in aggressive lymphoma and its significance in disease diagnosis and prognosis." (PMID 40260255, 2025). "The differences in CHI3L1 expression between lymphoma and control samples were analyzed using the lymphoma-related gene expression datasets GSE25638 and GSE56315, as well as their combined dataset (GSE25638 and GSE56315)." (PMID 40260255, 2025). "In this study, a nomogram prediction model for OS in aggressive lymphoma patients was constructed by integrating four indicators, namely, CHI3L1, LDH, β2-MG, and Cr." (PMID 40260255, 2025). "Through bioinformatics analysis and experimental validation, this study comprehensively examines the potential of CHI3L1 as a biomarker for the progression and prognosis of aggressive lymphoma." (PMID 40260255, 2025). "The serum CHI3L1 protein expression in patients with aggressive lymphoma was significantly higher than that in healthy controls (p<0.001)." (PMID 40260255, 2025). "Spearman correlation analysis revealed that serum CHI3L1 levels in invasive lymphoma patients were positively correlated with β2-MG, LDH, and creatinine (Cr), but negatively correlated with Hb." (PMID 40260255, 2025).
lymphoma (continued). "The results show that serum CHI3L1 levels were significantly elevated in lymphoma patients compared to healthy controls, with a highly significant difference (P < 0.001)." (PMID 40260255, 2025). "The expression of the CHI3L1 gene in PBMCs from 12 patients with aggressive lymphoma and 10 healthy individuals was detected via RT–qPCR." (PMID 40260255, 2025). "Through in-depth molecular mechanism studies and clinical validation, CHI3L1 is expected to be a key target in the diagnosis and treatment of aggressive lymphomas, and the survival rate and quality of life of patients will improve." (PMID 40260255, 2025). "Based on this cutoff, the 184 patients with invasive lymphoma were categorized into a CHI3L1 low-expression group (n=127) and a CHI3L1 high-expression group (n=57)." (PMID 40260255, 2025). "ROC analysis revealed that the AUC of CHI3L1 for predicting aggressive lymphoma was 0.933 (95% CI: 0.825~1.000), with a sensitivity of 83.3% and a specificity of 100%." (PMID 40260255, 2025). "In this study, we systematically combined bioinformatics analysis and experimental validation to thoroughly investigate the expression level of CHI3L1 in aggressive lymphomas and its prognostic value." (PMID 40260255, 2025). "The results revealed that the expression level of the CHI3L1 gene in patients with aggressive lymphoma was significantly greater than that in healthy controls (P < 0.01)." (PMID 40260255, 2025). "Using the GSE25638, GSE56315, and merged datasets, we analyzed CHI3L1 expression differences between lymphoma samples (tumor group) and normal control samples (normal group)." (PMID 40260255, 2025). "Although our study primarily focuses on CHI3L1 expression in lymphoma cells, the tumor microenvironment is a highly intricate network of cellular interactions." (PMID 40260255, 2025). "Validation experiments confirmed that CHI3L1 gene expression in PBMCs of patients with aggressive lymphoma was significantly higher than that in healthy individuals (p<0.01)." (PMID 40260255, 2025). "For experimental validation, we used qPCR to detect CHI3L1 gene expression in peripheral blood single nucleated cells, and the results revealed that the expression of CHI3L1 in patients with aggressive lymphoma was significantly greater than that in healthy controls." (PMID 40260255, 2025). "In the PPI network, 385 nodes were included, of which 11 nodes had direct interactions with CHI3L1 and 373 nodes had indirect interactions with CHI3L1, indicating that CHI3L1 is involved in the development and prognosis of lymphomas through interactions with these genes." (PMID 40260255, 2025). "However, the role of CHI3L1 in hematologic malignancies remains insufficiently explored, particularly regarding its expression characteristics and prognostic value in aggressive lymphomas." (PMID 40260255, 2025). "Moreover, CHI3L1 may contribute to lymphoma progression by regulating key biological processes." (PMID 40260255, 2025). "In conclusion, Cox regression analysis revealed that CHI3L1, LDH, β2-MG and Cr were all independent factors affecting the prognosis of aggressive lymphoma patients." (PMID 40260255, 2025). "By analyzing the GSE25638 and GSE56315 datasets, we found that CHI3L1 expression in lymphoma samples was significantly higher than that in normal samples, suggesting that high CHI3L1 expression may be closely related to the occurrence and progression of lymphomas." (PMID 40260255, 2025). "To investigate the biological functions of CHI3L1 in lymphoma development and prognosis in detail, we further performed functional enrichment analysis of the genes in the PPI network that have potential regulatory roles with CHI3L1." (PMID 40260255, 2025). "More importantly, follow-up of 184 patients with aggressive lymphoma revealed that patients in the nonsurviving group had significantly higher CHI3L1 levels than did those in the surviving group." (PMID 40260255, 2025).
plaque psoriasis (5 papers, 2017 to 2024). "Increased CCL18, CHI3L1 and AZU1 levels were detected in plasmas from plaque psoriasis, but we could not confirm their association with anti-CA IgA levels, which remains a limitation of the study." (PMID 33546306, 2021).
rectal cancer (5 papers, 2015 to 2023). A primary or metastatic malignant neoplasm that affects the rectum. "Therefore, the CHI3L1 rs4950928 C allele was reported to be associated with risk of rectal cancer and increased serum levels of CHI3L1 in Egyptians." (PMID 37902124, 2023).
sporadic Creutzfeldt-Jakob disease (5 papers, 2017 to 2025). A rare sporadic human prion disease characterized by rapidly progressive cognitive impairment in combination with variable neurologic signs and symptoms including myoclonus, visual or cerebellar problems, pyramidal or extrapyramidal features, or akinetic mutism. "In a separate study, CSF CHI3L1 levels were significantly higher in sporadic CJD patients compared to both neurologic controls and those with other neurodegenerative diseases." (PMID 39827337, 2025). "Histological analyses further demonstrated marked upregulation of CHI3L1 in the frontal cortex and cerebellum of sporadic CJD patients, correlating positively with GFAP levels, further implicating CHI3L1 in the neuroinflammatory processes driving disease progression." (PMID 39827337, 2025).
steatosis (5 papers, 2016 to 2025). Increased lipid within the cytoplasm of cells. "While no evident changes were observed in H&E staining in regards of degree of steatosis, immunofluorescence in liver frozen tissue showed an important decrease of CHI3L1 detection signal in CreLyz mice compared to WT controls." (PMID 37166517, 2023).
thyroid cancer (5 papers, 2020 to 2026). "We detect a number of recurrent fusions, such as those involving ANO3, RGS9, FUT5, CHI3L1, OR1D4, and LIPG in breast; IGF2 in colon; ETV1 in prostate; and IGF2BP3 and SIX2 in thyroid cancers." (PMID 32631391, 2020).
chronic hepatitis B (4 papers, 2018 to 2025). "Serum CHI3L1 levels were measured by ELISA in 78 AILDs patients, 65 chronic hepatitis B patients." (PMID 40352927, 2025).
dermatomyositis (4 papers, 2022 to 2024). Dermatomyositis (DM) is a type of idiopathic inflammatory myopathy characterized by evocative skin lesions and symmetrical proximal muscle weakness. "Both polymyositis (PM) and dermatomyositis (DM) are inflammatory muscle diseases characterized by muscle weakness, and Chi3l1 levels are significantly increased in PM/DM patients." (PMID 39769202, 2024).
experimental autoimmune encephalomyelitis (4 papers, 2017 to 2025). An autoimmune demyelinating disease of the central nervous system that is produced experimentally in animals by the injection of homogenized brain or spinal cord in Freund's adjuvant. "Knock-out animal models indicated a protective role of CHI3L1, as traumatic brain injury and experimental autoimmune encephalomyelitis were more severe in its absence." (PMID 33603109, 2021). "In an experimental autoimmune encephalomyelitis (EAE) model, CHI3L1 was highly expressed in the spinal cord, particularly in oligodendrocytes and microglia/macrophages." (PMID 40362399, 2025).
fatty liver (4 papers, 2014 to 2021). "In women with HIV and central obesity, the hepatic steatosis/fibrosis marker Chi3L1 and adiponectin decrease in conjunction with sST2 decreases following switch to RAL." (PMID 29746485, 2018). "Histological lipid grading together with Oil Red O staining results, and measurement of triglyceride levels suggest that altering Chi3L1 protein function with specific targeted agents to Chi3L1 may be beneficial in reducing hepatic steatosis as well." (PMID 33498326, 2021).
Granuloma (4 papers, 2020 to 2026). A compact, organized collection of mature mononuclear phagocytes, which may be but is not necessarily accompanied by accessory features such as necrosis. "Among the other differentially expressed genes, notable upregulation of CHIT1 and CHI3L1 is observed in cardiac granulomas." (PMID 40521183, 2025). "Bulk gene expression deconvolution of this data supported a significant increase in the frequency of several populations in untreated TB granuloma compared with control LN, including the SPP1+CHI3L1+ macrophage." (PMID 41489684, 2026). "The concurrent expression of Acetyl-H3K9, Chi3l1, CSF1R, IL4R, TGFß, and Jak3/Stat6 in granulomas of cardiac sarcoidosis promotes the polarization of macrophages toward the M2 phenotype, facilitating anti-inflammatory conditions and driving fibrotic processes." (PMID 40521183, 2025). "The concurrent expression of Acetyl-H3K9, Chi3l1, CSF1R, IL4R, TGFß, and Jak3/Stat6 in granulomas of CS further reinforces macrophages towards M2 polarization, thereby leading to anti-inflammatory states and fibrosis." (PMID 40521183, 2025).
hepatitis B (4 papers, 2019 to 2024). "This suggests that the level of CHI3L1 among outpatients with chronic HIV in our study reflects a low level of systemic inflammation, relative to patients hospitalized with acute life-threatening infections or another chronic viral infection (hepatitis B)." (PMID 36560606, 2022).